C17orf50 (chromosome 17 open reading frame 50)
Tractability: No criterion of Open Targets' tractability assessment is met for any kind of drug.
Gene: Protein-coding gene on chromosome 17 (35,760,887 to 35,765,079, forward strand). Ensembl gene ENSG00000270806.
Subcellular location (Human Protein Atlas): Nucleoplasm
Gene Ontology:
Molecular function: protein binding
Cellular component: nucleoplasm
Genetic constraint (gnomAD): Loss-of-function variants: 17 observed, 14.99 expected, observed/expected ratio (o/e) 1.13, 90% interval 0.77 to 1.68. The upper end of that interval is the gene's LOEUF score, 1.68, which puts it in group 6 of 6, group 1 being the genes least tolerant of losing a copy. Missense variants: 271 observed, 216.85 expected, observed/expected ratio (o/e) 1.25, 90% interval 1.13 to 1.38. Synonymous variants: 125 observed, 102.47 expected, observed/expected ratio (o/e) 1.22, 90% interval 1.05 to 1.41.
Homologues: Orthologues: chimpanzee C17H17orf50 (98% identical), macaque C16H17orf50 (87% identical), rabbit C17orf50 (75% identical), dog C17orf50 (70% identical), mouse 1700020L24Rik (67% identical), rat C10h17orf50 (62% identical), guinea pig C17orf50 (60% identical).